HNRNPD (heterogeneous nuclear ribonucleoprotein D)
Diseases named in the same sentence as HNRNPD in open-access papers (continued):
Sharing a sentence is not in itself a finding about the gene and the disease.
oral cancer (2 papers, 2022). "Additionally, one previous report demonstrated a strong association between nuclear expression of hnRNPD and poor prognosis in oral cancer patients and suggested its diagnostic utility in this malignancy." (PMID 35741145, 2022). "Then by promoter deletion analysis, site-directed mutagenesis and ChIP assays established the role of NFκB in transcriptional up regulation of hnRNPD in oral cancer cells." (PMID 35396527, 2022). "Present study, for the first time demonstrate the involvement of transcription factor NFκB (RelA) in transcriptional up regulation of human hnRNPD in oral cancer and suggest the role NFκB (RelA)-hnRNPD axis in oral cancer." (PMID 35396527, 2022). "Spearman’s correlation analysis revealed a strong positive (p < 0.0001) correlation (r = 0.5980) between hnRNPD and NFκB (RelA) expression in oral cancer tissue." (PMID 35396527, 2022). "On the other hand in oral cancer tissue specimens displayed elevated expression of hnRNPD and NFκB in nuclear compartment." (PMID 35396527, 2022). "A study involving a proteomics-based approach identified numerous protein markers, namely prothymosin alpha (PTMA), S100A7, 14-3-3ζ, 14-3-3δ, hnRNPD, and hnRNPK, used for distinguishing between normal mucosa, dysplasia, and oral cancer." (PMID 35741145, 2022). "Over-expression of nuclear hnRNPD in oral cancer compared to that present in normal oral tissues is associated with poor prognosis." (PMID 35741145, 2022). "In view of our findings on transcriptional up regulation of hnRNPD expression by NFκB in oral cancer cells, it was of interest to validate these results in clinical specimen of oral cancer patients." (PMID 35396527, 2022). "Over-expression of hnRNPD has been reported in thyroid, lung, colon, esophageal, breast, and oral cancers." (PMID 35741145, 2022). "Thus, results of the present study for the first time convincingly demonstrate NFκB (RelA) mediated transcriptional upregulation of hnRNPD expression in oral cancer." (PMID 35396527, 2022). "Finally, the expression of hnRNPD and NFκB in clinical specimen from 37 oral cancer patients was assessed and subjected to Spearmen’s Correlation analysis which revealed a strong positive correlation between the two." (PMID 35396527, 2022). "Therefore, we analyzed the expression of hnRNPD and NFκB (RelA) in clinical specimens from 37 oral cancer patients (N = 37) and oral mucosa from 10 normal subjects by immunohistochemistry." (PMID 35396527, 2022). "Treatment of oral cancer cells by PDTC resulted in drastic reduction in transcript and protein level of hnRNPD." (PMID 35396527, 2022).
squamous cell carcinoma (2 papers, 2013 to 2022). A carcinoma arising from squamous epithelial cells. "The poorly differentiated squamous cell carcinoma displayed 100% (eight cases) immunoreactivity for hnRNPD as compared to 87.5% (seven cases) for p40." (PMID 35741145, 2022). "Both p40 and hnRNPD are located in the nucleus of squamous cell carcinoma cells of the oral cavity, which is in agreement with previous reports." (PMID 35741145, 2022). "The poorly differentiated squamous cell carcinoma tissue specimens showed 100% positivity for hnRNPD staining in comparison to p40 (87.50% positivity)." (PMID 35741145, 2022). "Thus, both p40 and hnRNPD proteins showed nuclear immunostaining in 38 out of 46 squamous cell carcinoma specimens." (PMID 35741145, 2022). "The p40 and hnRNPD showed equal sensitivity (80.95%) for squamous cell carcinoma, whereas hnRNPD emerged as marginally more specific than p40 with 88.23% specificity and 89.47% positive predictive value in comparison to p40 with 85.29% specificity and 87.17% positive predictive value." (PMID 35741145, 2022).
abnormal vision (1 paper, 2016). "Heterogeneous nuclear ribonucleoprotein D0 (hnRNP D0), also known as AU-rich element RNA-binding protein 1 (AUF1), is a well-characterized ARE-binding factor that destabilizes mRNA, while human (Hu) antigen proteins of the ELAV (embryonic lethal, abnormal vision) family are known to stabilize mRNA." (PMID 27437398, 2016).
amyotrophic lateral sclerosis (1 paper, 2024). Amyotrophic lateral sclerosis (ALS) is a neurodegenerative disease characterized by progressive muscular paralysis reflecting degeneration of motor neurons in the primary motor cortex, corticospinal tracts, brainstem and spinal cord. "Our results reveal significant nuclear loss of hnRNPD, hnRNPC and hnRNPA1 in the frontal cortex of frontotemporal lobar degeneration compared to amyotrophic lateral sclerosis but not in the motor cortical neurons or Betz cells of amyotrophic lateral sclerosis cases." (PMID 39670112, 2024).
chronic myeloid leukemia (1 paper, 2021). "Recently, hnRNPD overexpression was found to be involved in the induction of chronic myelogenous leukemia (CML)." (PMID 33767590, 2021).
clear cell renal cell carcinoma (1 paper, 2024). "HNRNPD can participate in cellular physiology, including the cell cycle and apoptosis, and plays roles in clear cell renal cell carcinoma (ccRCC) by modulating circRNA biogenesis and the mRNA levels of key genes, such as CDK1." (PMID 39180763, 2024).
diabetes (1 paper, 2021). "Cytokine-induced HNRNPD expression has been linked with increased rates of beta cell apoptosis in patients with diabetes, while reduced HNRNPD expression is linked to survival of pancreatic beta cells." (PMID 34301309, 2021).
dysplasia (1 paper, 2015). A usually neoplastic transformation of the cell, associated with altered architectural tissue patterns. "Further, ROC analysis showed an area under the curve (AUC) of 0.725 and 0.782 for dysplasia and OSCCs respectively for nuclear hnRNPD overexpression with high specificity, implicating its potential utility in distinguishing these tissues from normal epithelium." (PMID 26318153, 2015).
endotoxemia (1 paper, 2022). "The gross phenotypic characteristics of our germline hnRNPDΔx3,4 mice resembled those of whole body hnRNPD null mice; as did their enhanced sensitivity to endotoxemia." (PMID 35222366, 2022).
HIV-1 infection (1 paper, 2019). The type species of lentivirus and the etiologic agent of acquired immunodeficiency syndrome (AIDS). "It has been previously demonstrated that HIV-1 infection induces cytoplasmic retention of RBPs harboring prion-like domains, including hnRNPA1 and hnRNPD." (PMID 31695598, 2019).
leukemia (1 paper, 2025). A malignant (clonal) hematologic disorder, involving hematopoietic stem cells and characterized by the presence of primitive or atypical myeloid or lymphoid cells in the bone marrow and the blood. "While PSMA3, LRRC1, HNRNPD, and FAM98A demonstrated strong binding to HHT in vitro using purified proteins, their weaker engagement in leukemia cellular models highlights fundamental differences between simplified biochemical systems and complex physiological environments." (PMID 41472850, 2025).
myopia (1 paper, 2022). "No previous report has implicated HNRNPD in myopia development." (PMID 35153787, 2022).
Obesity (1 paper, 2025). Accumulation of substantial excess body fat. "Obesity also consistently altered 5 proteins in DMBA-exposed mice, including HNRNPC, HNRNPD, HSPA9, RPL36A, and KCTD12." (PMID 39910959, 2025).
proteinopathies (1 paper, 2024). "Interestingly, nuclear loss of hnRNPD (DL, AB) was found to associate with increasing cytoplasmic pTDP-43 as well as with decreasing nuclear hnRNPA1, A0 and C to suggest the involvement of this understudied subfamily in the pathogenesis of TDP-43 proteinopathies." (PMID 39670112, 2024).
renal carcinoma (1 paper, 2024). A carcinoma arising from the epithelium of the renal parenchyma or the renal pelvis. "Taken together, these data demonstrated that HNRNPD exhibited an anti-tumour role in human renal cancer by modulating the ratio of the linear splicing to the backsplicing of key genes, including CDK1." (PMID 39180763, 2024).
testicular cancer (1 paper, 2021). A primary or metastatic malignant neoplasm that affects the testis. "As expected, EFTUD2, ELAVL2, HNRNPD, KIT, NCL, NRXN1 and RPS8 were significantly varied in testicular cancer patients." (PMID 33746583, 2021). "Among 25 hub genes, EFTUD2, HNRNPD, KIT, NCL and RPS8 were significantly upregulated in testicular cancer patients, however, ELAVL2 and NRXN1 were significantly downregulated using GEPIA online database." (PMID 33746583, 2021).
cancer (55 papers, 2007 to 2025). A tumor composed of atypical neoplastic, often pleomorphic cells that invade other tissues. "Loss of hnRNPA1, hnRNPC1, or hnRNPD induces cell death and proliferation arrest in cancer models and these proteins were decreased in response to peptide treatment." (PMID 33859938, 2021). "Interestingly, some NDD hnRNPs have already been implicated in cell division through cancer studies, including hnRNPD, hnRNPK, SYNCRIP, and hnRNPU." (PMID 33874999, 2021). "Previous study has revealed that ebv-sisRNA-1 and ebv-sisRNA-2 interact with human HNRNPL and HNRNPD proteins, probably implicating in the pro-cancer-related phenotypes." (PMID 40579704, 2025). "HnRNPD is part of the hnRNP family and has been reported to function as an oncogene in a variety of cancers." (PMID 37538116, 2023). "In another study, HNRNPD mRNA levels in tumor tissues and corresponding paracancerous tissues were compared in 154 patients with 19 kinds of cancers." (PMID 32452829, 2020). "Moreover, HNRNPD was functionally active in cancer samples, characterised by cell‐free epigenomes with upregulated H3K4me3 levels, lower DNA methylation and reduced NDR occupancy." (PMID 39909829, 2025). "Taken together, these data suggest that HNRNPD modulation could be used to sensitize cancer cells to various antitumoral agents." (PMID 30799487, 2019). "From this subset, we prioritized five candidates (PSMA3, EWSR1, LRRC1, HNRNPD, and FAM98A) based on their SNR rankings, established roles in cancer pathways (e.g., proteasome function, RNA processing, and transcriptional regulation)." (PMID 41472850, 2025). "We observed a tendency for shorter fragments in the HNRNPD gene region in cancer samples, but not in TMEM150C." (PMID 39909829, 2025).
tumor (45 papers, 2007 to 2026). "Analysis of the TCGA-HNSC cohort revealed that HNRNPD is significantly up-regulated in 519 tumor tissues versus 44 normal samples, and similar overexpression was observed in NPC tissues in the GSE12452 dataset (31 NPC vs. 10 normal tissues)." (PMID 41194937, 2025). "Prior research has elucidated that lncRNAs can modulate the mRNA stability of specific target genes by interacting with hnRNPD, thereby exerting a notable influence on tumor initiation and progression." (PMID 39350250, 2024). "We have presented data to show that for the alterations in cell growth and apoptosis observed in either the KO cells or the ccRCC tumours, the key HNRNPD downstream effector is CDK1." (PMID 39180763, 2024). "It was found that only CIRBP, NCL, and HNRNPD are related to both mitochondrial function and autophagy, as well as anti-tumor biological activity." (PMID 36013308, 2022). "As evident from these results, hnRNPD showed intense staining in 23 (50%) cases with more than 70% tumor cells reactivity in 11/23 (47.82%) cases." (PMID 35741145, 2022). "hnRNPD showed overall improvement in immunohistochemical staining in terms of tumor-specific reactivity and intensity." (PMID 35741145, 2022). "Cox regression multivariate analysis was carried out to determine the prognostic potential of nuclear hnRNPD for OSCCs in comparison with the other clinical parameters including age, gender, histological grade, tumor size, nodal status and stage." (PMID 26318153, 2015). "Overexpression of nuclear hnRNPD showed significant correlation with increasing tumor size (p = 0.005, OR = 2.4, 95 % C.I. = 1.3–4.6) and tumor stage (p = 0.02, OR = 2.3, 95 % C.I. = 1.0–5.2)." (PMID 26318153, 2015). "Furthermore, ccRCC tumours have higher levels of HNRNPD, lower levels of circCDK1, and higher levels of CDK1 mRNA and protein." (PMID 39180763, 2024). "Based on TCGA data, ccRCC tumour specimens have higher HNRNPD mRNA levels than normal specimens." (PMID 39180763, 2024). "However, hnRNPD displayed marginally higher (88.23%) specificity for tumor cells as compared to that of p40 (85.29%)." (PMID 35741145, 2022). "However, in the case of hnRNPD, there was an overall increase in the tumor cell’s immunoreactivity in 20/31 (64.51%) cases as compared to p40 (11/31; 35.48%)." (PMID 35741145, 2022). "Suppressing the expression of HNRNPD significantly inhibited cell cycle progression and proliferation in vitro, and also increased apoptosis, inhibited tumor cell proliferation and prolonged survival in tumor-bearing mice." (PMID 32452829, 2020). "HNRNPD plays similar regulatory roles related to circRNA biogenesis in both HEK293T cells and ccRCC tumour cells." (PMID 39180763, 2024). "Consistent with the ATG7 negative regulation of HNRNPD in vitro cultured UMUC3 cells, HNRNPD protein expression was markedly increased in xenograft tumor tissues attained from nude mice injected with UMUC3(shATG7) cells, and the similar change of NCL protein expression." (PMID 31016112, 2019). "Finally, to assess the potential clinical relevance of HNRNPD, we assessed whether its knockout could sensitize HeLa cells to treatment with CPT, the precursor of a broad class of antineoplastic drugs widely used for the treatment of several tumours." (PMID 30799487, 2019).
infection (7 papers, 2014 to 2024). The state of being infected such as from the introduction of a foreign agent such as serum, vaccine, antigenic substance or organism. "Heterogeneous nuclear ribonucleoprotein D (HNRNPD), epsin 2 (EPN2), and tripeptidyl peptidase 1 (TPP1), among others, showed reduced protein levels when cotransfected with CTSW compared to their levels in the green fluorescent protein (GFP) control, regardless of infection." (PMID 35867415, 2022).
neurodegenerative disease (1 paper, 2020). A disorder of the central nervous system characterized by gradual and progressive loss of neural tissue and neurologic function. "HTT, neurofilament heavy chain (NF‐H), Tau (MAPT), FUS, TDP‐43, HNRNPA1, HNRNPD, RPL7 and actin (ACTB, found aggregated in Hirano bodies in several neurodegenerative diseases; Hirano, 1994), were selectively aggregated upon RNase A/T1 treatment of human neuronal lysates." (PMID 32945072, 2020).
HNRNPD also shares sentences with these, for which no sentence is quoted: hepatocellular carcinoma (8 papers); Sepsis (6); viral infection (4); chronic obstructive pulmonary disease (3); Enterovirus Infections (3); osteosarcoma (3); triple-negative breast carcinoma (3); chronic superficial gastritis (2); neuroblastoma (2); prostate carcinoma (2); adenocarcinoma (1); allergic asthma (1); anaplastic large cell lymphoma (1); asthenozoospermia (1); asthma (1); autoimmune disease (1); bacterial Sepsis (1); brain disease (1); breast (1); breast tumor (1); celiac disease (1); chronic gastritis (1); chronic kidney disease (1); chronic lymphocytic leukemia (1); colitis (1); dermatitis (1); diabetic nephropathy (1); esophageal squamous cell carcinoma (1); frontotemporal lobar degeneration (1); glioblastoma (1).
A further 28 diseases each share a sentence with HNRNPD in 1 paper.